ENO1 (enolase 1)
Diseases named in the same sentence as ENO1 in open-access papers (continued):
Sharing a sentence is not in itself a finding about the gene and the disease.
tumor (continued). "The expression of ENO1 also potentially contributed to the stages of tumor development." (PMID 33643901, 2020). "Taken together, the varied expression of ENO1 in different types and stages of cancers implied that the effects of ENO1 may vary in different cancers and at different tumor stages." (PMID 33643901, 2020). "In tumor cells, ENO1 is up-regulated and supports the Warburg effect." (PMID 32795333, 2020). "CircRNA-ENO1 and its linear mRNA ENO1 promotes glycolysis and tumor formation in LUAD." (PMID 31911754, 2020). "ENO1 expression was significantly different in tumor and corresponding normal tissues." (PMID 33643901, 2020). "The boxplots of ENO1 expression in tumor and normal tissues were generated by GEPIA." (PMID 33643901, 2020). "We infer that ENO1 may be released into serum or tissues in an exosome-dependent manner, thereby performing its biological function and promoting tumor progression." (PMID 33184263, 2020). "In this study, differential expression of ENO1 in different stages of CESC, HNSC, BLCA, LUAD, KICH, PAAD, and LIHC was identified, indicating ENO1 could be a marker for tumor staging." (PMID 33643901, 2020). "The correlation of ENO1 expression with prognosis, tumor stage, and levels of tumor immune infiltrates in different cancers remains unclear." (PMID 33643901, 2020). "Finally, in vivo assays further validated that circ-ENO1 promoted tumor growth and metastasis in LUAD." (PMID 31767835, 2019). "Depending on its location in the tumor, ENO1 can exert multiple functions." (PMID 31798634, 2019). "Emerging studies have documented that ENO1 promotes tumor progression of lung cancer." (PMID 31767835, 2019). "Consequently, adoptive transfer of an anti-ENO-1 antibody inhibited the formation of tumor metastasis in the lung and the bones." (PMID 31106201, 2019). "As a glycolytic enzyme, ENO1 acts as a metabolic tumor promoter by contributing to Warburg effect." (PMID 31709724, 2019). "In vivo experiments certified that circ-ENO1 drove tumor growth and metastasis in vivo." (PMID 31767835, 2019). "However, we have demonstrated the presence of anti-ENO1 autoantibodies in PDA patient sera and of anti-ENO1-specific T cells into the tumor." (PMID 29462900, 2018). "The enolase ENO1 (α-enolase) is a glycolytic enzyme responsible for the conversion of 2-phosphoglycerate to phosphoenolpyruvate and functions in aerobic glycolysis, contributing to the Warburg effect in tumor cells." (PMID 29497031, 2018). "Therefore, it should be reasonable that ENO1 has potential value to be a tumor marker for PDAC diagnosis." (PMID 29483925, 2018). "ENO1 has been proposed to be a potential tumor biomarker of chemo-resistance and overall prognosis." (PMID 30301274, 2018). "Having shown that ENO1 and Homer3 mediated cancer cell growth and metastasis induced by WBP2 overexpression, we explored the underlying mechanism of WBP2 acting as a key regulator of tumor development." (PMID 29497031, 2018). "ENO1 is involved in a variety of metabolic pathways and is closely related to the tumor occurrence." (PMID 29522283, 2018). "Our results showed that the ENO1 level was positively correlated with tumor progression in the peripheral blood of PDAC patients as well as in PDAC tissues, which indicated that ENO1 concentration may be associated with local tumor and vascular invasion." (PMID 29483925, 2018). "It is known that ENO1 knockdown induces a dramatic increase of the sensitivity to microtubule-targeted drugs (e.g., taxanes and vincristine) in different tumor cell lines, due to ENO1-tubulin interactions, suggesting a role for ENO1 in modulating the cytoskeletal network." (PMID 28086938, 2017).
tumor (continued). "Therefore, ENO1 was proposed to be a potential tumor biomarker of chemoresistance and overall prognosis." (PMID 28548950, 2017). "We found that ENO1 silencing in tumor cells affected the expression of all enolase isoforms, confirming that the inhibition of enolases decreases proliferation and also affects in vivo tumor growth." (PMID 26734996, 2016). "Expression of Eno-1 also correlated with tumor size and venous invasion." (PMID 26918350, 2016). "In contrast, ENO1 can be alternatively translated into a c-Myc promoter binding protein, which is localized to the nucleus to bind to the c-Myc promoter and suppress the transcription of c-Myc14, 16, suggesting a tumor suppressor function." (PMID 27767175, 2016). "In this study, we explored the hypothesis that ENO1 is one of the leading regulators of the Warburg effect and thus plays a major role in carcinogenesis and tumor maintenance." (PMID 26734996, 2016). "Consequently enolase-1 increases the survival rate, proliferation, and the invasive and metastatic ability of the tumor cells." (PMID 27110560, 2016). "Metastatic PANC-1/M cells derived from a liver metastasis, following orthotopical injection of PANC-1 cells in the pancreas, expressed higher levels of surface ENO1 compared to the primary tumor cells, suggesting a role for surface ENO1 in facilitating tumor spreading." (PMID 25860938, 2015). "Anti-ENO1 mAb treatment led to a reduced number of tumor masses compared to control treatment." (PMID 25860938, 2015). "In both cases, specific treatment with anti-ENO1 mAb was effective in inhibiting tumor growth." (PMID 25860938, 2015). "Using animal models, we demonstrated that tumor cells reduce the circulating levels of anti-ENO1 Ab through physical absorption and neutralization of anti-ENO1 Ab with surface-expressed and secreted ENO1, respectively." (PMID 26551021, 2015). "Mice were pre-treated for 3 days with anti-ENO1 or control Abs prior to tumor challenge." (PMID 25860938, 2015). "Conversely, although the total amount of ENO1 was not increased in metastatic PANC-1/M cells, its surface distribution was clearly augmented in these cells, confirming that surface ENO1 may play a crucial role in tumor metastasis." (PMID 25860938, 2015). "We observed that a substantial amount of adoptively transferred anti-ENO1 Ab accumulated at the tumor area 24 h after i.v. injection, which may be due to absorption of transferred Ab by tumor cells through surface ENO1." (PMID 26551021, 2015). "Hypoxia, a condition that characterizes tumor growth in vivo, up-regulates ENO1 expression; therefore, we cannot rule out that the surface expression of ENO1 results from a general increase of ENO1 transcription and translation." (PMID 25860938, 2015). "Again, treatment with the anti-ENO1 mAb substantially reduced metastatic tumor masses in livers." (PMID 25860938, 2015). "Although some studies demonstrated increased ENO-1 cell surface expression in late and end stages of cancer, its contribution to tumor progression and metastasis formation still remains speculative and requires further investigations." (PMID 25407528, 2014). "Moreover, ENO1 is found on the surface of CCA cells and its overexpression is associated with poor prognosis and tumor invasiveness." (PMID 25058392, 2014). "Therefore, the key determinant that instigates either tumor growth or tumor regression is translation of ENO-1 gene towards Enolase or MBP-1 expression respectively (Enolase/MBP-1 ratio)." (PMID 25621294, 2014). "We hypothesize that ENO1 may contribute to tumor progression via the PI3K/Akt pathway mediating the activity of Cyclin D1, Cyclin E, and NF-κB, which will eventually result in hyperphosphorylation of Rb and downregulation of E-cadherin mediated classical EMT." (PMID 24650096, 2014).
tumor (continued). "ENO1 that is expressed in most tissues is known to undergo a multitude of post-translational modifications in normal and tumor tissues, some of which are different in normal and diseased states and may have value in therapeutic and diagnostic strategies." (PMID 24009698, 2013). "We propose that ENO1 links plasminogen with the uPA/uPAR complex in close proximity on tumor cells that express endogenous plasminogen, uPA, and uPAR, resulting in efficient generation of plasmin and subsequent proteolytic activity on the surface of tumor cells." (PMID 23894455, 2013). "Targeting surface ENO1 may selectively target tumor cells while leaving the majority of normal cells unharmed." (PMID 23894455, 2013). "Because the coding sequence of ENO1 lacks a transmembrane or a GPI-linkage section, the mechanism by which ENO1 is transported to and displayed on the cell surface and the importance of ENO1 on the surface of tumor cells remains unclear." (PMID 23894455, 2013). "We next examined the role of surface ENO1 on tumor cells in vivo with 4 different animal models." (PMID 23894455, 2013). "The overexpression of ENO1 was not statistically associated with clinicopathologic features such as age, ovariohysterectomy, size and grade of tumor, histological classification, location of affected glands, and expression of ER, PR, and HER2." (PMID 22014164, 2011). "ENO1 may act as a stress protein that promotes hypoxic tolerance in tumor cells by increasing anaerobic metabolism." (PMID 22014164, 2011). "Enolase 1(ENO1), a phosphopyruvate dehydratase, is a key glycolytic enzyme involved in anaerobic metabolism under hypoxic conditions of cancer growth, and a cell surface plasminogen receptor for tumor invasion." (PMID 22110952, 2011). "The cell lines showed a higher relative concentration of ENO1 than any of the primary tumours." (PMID 16359544, 2005). "Additionally, ENO1 inhibitor, ENOblock significantly reducing tumor volume and weight." (PMID 40665335, 2025). "Consequently, we propose an innovative mechanism whereby ENO1 increases the levels of cytoplasmic glycolytic intermediates (ATP and lactate) to cooperatively regulate these two energy-responsive growth signaling pathways, thereby sustaining tumor progression." (PMID 41168198, 2025). "Additionally, Esc inhibited tumor growth by down-regulating ENO1 expression in vivo." (PMID 40740998, 2025). "The in vitro and in vivo experiments demonstrated that tumor-intrinsic ENO1 deficiency impedes tumorigenesis and reshapes the immune landscape of the TME by facilitating the infiltration of CD8+ T cells, suggesting a pivotal role for ENO1 in regulating the tumor immune microenvironment (TIME)." (PMID 40665335, 2025). "ENO1, best known for catalyzing glycolysis’ ninth enzymatic step, has been identified as a melatonin-regulated protein that mediates downstream metabolic processes, which is mainly involved in the glycolytic process of tumor cells to provide energy support for the survival of tumor cells." (PMID 40756978, 2025). "However, as a glycolytic enzyme, the role of ENO1 in regulating tumor progression and therapeutic resistance via glycolysis remains unclear." (PMID 41168198, 2025). "Furthermore, while glycolytic genes (HK2, GAPDH, ENO1) correlate with poor survival, the analysis cannot establish whether their upregulation drives tumour aggression or is a secondary effect of MYCN‐mediated metabolic reprogramming." (PMID 41420301, 2025). "Additionally, Kcr and Khib modifications were also verified to contribute to gastrointestinal cancer metastasis, with elevated ENO1 Kcr in human CRC tissues promoting CRC cell invasion, migration, and growth by increasing ENO1 activity and upregulating tumor-associated expression." (PMID 38315203, 2024). "In addition, we investigated the role of ENO1 in USP21-mediated CCA tumor progression." (PMID 38385089, 2024). "Moreover, ENO1 overexpression in PDA tissues correlated with tumor progression." (PMID 37910256, 2023).
tumor (continued). "Besides CD44, the tumor-suppressive action of extracellular ENO1 and MSN was mediated by Mtdh." (PMID 36923539, 2023). "Therefore, TYRO3 expression inhibition in drug-resistant cells may reduce ENO1 expression, down-regulating the proliferation and migration of tumor cells by restricting glucose utilization and partial ATP production." (PMID 37116196, 2023). "Tumour-like CAFs (tCAFs): We observed strong differential expression of proliferation-, migration- and metastasis-associated genes (e.g., PDPN, MME, TMEM158 and NDRG1) as well as stress-response-associated genes (e.g., ENO1), and GAPDH in a small cluster (n = 786 cells)." (PMID 37463917, 2023). "Meanwhile, CAD-14 could inhibit tumor growth by inhibiting ENO1 in vivo." (PMID 37959729, 2023). "In tumor tissues, overexpressed ENO1 may be released into the peripheral blood through apoptosis of tumor cells or other pathways, thereby leading to up-regulation of ENO1 protein expression in the peripheral blood of tumor patients." (PMID 37959729, 2023). "Meanwhile, CAD-14 may inhibit tumor growth by inhibiting ENO1 in vivo." (PMID 37959729, 2023). "In addition, the phosphorylation levels of PI3K and AKT were also significantly reduced, suggesting that ENO1 may affect tumor cell activity by mediating the PI3K/AKT pathway and the corresponding downstream signaling pathways." (PMID 35434271, 2022). "To explore the potential mechanism underlying ENO1-mediated regulation of drug resistance in CRC cells, we intended to identify a correlation between ENO1 and cell characteristics such as angiogenesis, apoptosis, and cell cycle in lung, kidney, central nervous system, and other tumor tissues." (PMID 36620599, 2022). "This diversification may be tumor specific and related to the subcellular localization of ENO1." (PMID 35434271, 2022). "Thus, the age-related increase in ENO1 levels may indicate the metabolic reprogramming of prostate cells, which may lead to pre-neoplasia and, eventually, neoplasia." (PMID 35886909, 2022). "It indicated that exosomal ENO-1 might gather proteolytic activity on the BC-cell surface or enlarge the cytoplasmic pool of ENO-1, thereby modulating the expression of the genes related to cell proliferation, migration, and inflammation to promote tumor progression." (PMID 34039961, 2021). "Moreover, WTAP silencing reduced mRNA levels of ENO1 in C5RN-cultured tumor cells." (PMID 34312368, 2021). "Thus, the various cellular localizations, as well as the different pathways regulating ENO1 functions in the different types of tumor cells, may account for the inconsistence of the experimental results reported thus far." (PMID 33628097, 2021). "Besides, we preliminarily investigated the potential mechanism of ENO1-mediated tumor growth, that ENO1 might promote the biological properties of LCSCs by AMPK/mTOR pathway." (PMID 33579362, 2021). "There is still uncertainty, however, whether ENO1 is a determinant of tumor stage." (PMID 33643901, 2020). "Therefore, ENO1 may be used as a potential biomarker for predicting prognosis, tumor stage, and immune infiltration in CESC, LUAD, and KICH patients." (PMID 33643901, 2020). "Additionally, patients with advanced cancers were underrepresented in TCGA cohort, particularly the ones with KICH, while ENO1 might show different biological activities at different tumor stages." (PMID 33643901, 2020). "Hence, results above indicated that circ-ENO1 promoted tumor growth and metastasis in LUAD in vivo." (PMID 31767835, 2019). "Moreover, ENO1 as a plasminogen receptor on the tumor cell surface could induce extracellular matrix degradation, tumorigenesis, and cancer invasion during pathologic conditions." (PMID 29497031, 2018).
tumor (continued). "ENO1 localized on the cell membrane can activate the plasminogen system as a fibrin soluble plasminogen receptor, and the plasminogen system can promote the invasion and metastasis of tumor cells through participation of basement membrane and extracellular matrix remodeling." (PMID 29483925, 2018). "This may be associated with the up-regulation of ENO1 which started at the very earliest neoplastic stage of PDAC, increased with the developing of PDAC, and decreased in the peripheral blood by necrosis and turnover of primary tumor cells at the latest stage." (PMID 29483925, 2018). "All anti-tumor restoring effects of PI3K inhibitors strongly suggest that small pharmacological inhibitors that target PI3Kγ or δ isoforms or all isoforms together can be a suitable powerful combinatorial partner to enhance the antitumor efficacy of ENO1 vaccination." (PMID 29462900, 2018). "Therefore, the presence of anti-ENO autoantibodies and T cells prompted us to verify the hypothesis of eliciting a strong anti-ENO1 immune response by a DNA vaccine, able to counteract tumor progression." (PMID 29462900, 2018). "To confirm the MS identification of the protein, we incubated the proteomic maps obtained from the tumor cells of 10 anti-ENO1 Ab+ (patients 22, 23, 24, 25, 26, 27, 29, 31, 32, 33) and 4 anti-ENO1 Ab- patients (patients 28, 30, 34, 35) with a commercially available anti-ENO1 polyclonal Ab." (PMID 27906678, 2017). "Removal of tumor may lead to a reduction in the number of Tregs and circulating ENO1." (PMID 26551021, 2015). "Recently, many lines of evidence suggested that ENO1 might contribute to tumor malignancy." (PMID 22014164, 2011). "Surface ENO1 interacts with monocarboxylate transporter 4 (MCT4) for lactate secretion, which recruits M2 macrophages and promotes an immunosuppressive tumor microenvironment (TME)." (PMID 41629269, 2026). "The present study uncovered a DCDC2/ENO1/FGL1/LAG-3 axis and communication between ICC tumor cells and CD8+ T cells." (PMID 40533767, 2025). "Dysregulation of key enzymes—including GAPDH, enolase 1 (ENO1), pyruvate kinase M2 (PKM2), and lactate dehydrogenase A (LDHA)—drives tumor growth and metastasis." (PMID 41204384, 2025). "The expression of glycolytic genes HK2, GAPDH and ENO1 were analysed in the context of MYCN amplification, INSS tumour stage progression and overall event free survival using KM plots." (PMID 41420301, 2025). "Subsequent IHC staining showed significantly reduced expression of ENO1, p-PI3K, and p-AKT in tumor tissues from the combination therapy groups." (PMID 41353343, 2025). "In this study, we identified a novel mechanism by which autophagy-dependent secretion of ENO1 drives TMZ chemoresistance and immune evasion in GBM through bidirectional crosstalk between tumor cells and TAMs." (PMID 41353343, 2025). "Enrichment of hypoxia-related terms with leading gene ENO1 suggested that MSC1 cells not only deploy hypoxic responses, but also activate feedback mechanisms to prevent tumor-promoting excessive hypoxic signaling." (PMID 40564222, 2025). "In this study, we revealed that ENO1 is protected from ubiquitin-mediated degradation by EMC2 29,30,46 and promotes tumor progression by stabilizing B-MYB mRNA." (PMID 40303285, 2025). "Glycolysis genes HK1, GAPDH, ENO1, LDHA, and PKM, and cell cycle genes (except CCND2) were among the most tumor-specific genes." (PMID 39774001, 2025). "The further analysis of the H-score in different regions of the tumor and control tissues showed significant differences in PADI2 (p < 0.0001), citENO1 (p < 0.0001), and ENO1 (p = 0.0016)." (PMID 40573960, 2025). "For example, core glycolysis genes such as ALDOA, GAPDH, ENO1, and PKM2 are high in both tumor and immune cells." (PMID 39774001, 2025).